SST (somatostatin)
Diseases named in the same sentence as SST in open-access papers (continued):
Sharing a sentence is not in itself a finding about the gene and the disease.
tumor (continued). "SSTR1 hypermethylation in 64% of cases was correlated with tumor size (P = 0.037), stage (P = 0.037), SST methylation (P < 0.001), and expression of galanin (P = 0.03), GALR2 (P = 0.014), TAC1 (P = 0.023), and tachykinin receptor type 1 (TACR1) (P = 0.003)." (PMID 25734919, 2015). "SST analogs labeled with therapeutic radionuclides, such as 111In, 90Y, 177Lu, and 213Bi, are able to specifically bind to SSTRs on tumor cells and deliver an effective radiation dose to tumors with minimal damage to normal tissues." (PMID 25879040, 2015). "It has been shown that SST can suppress tumor growth through distinct mechanisms; these include regulation of the immune system, inhibition of growth factors, and reduction in vascularization." (PMID 26251921, 2015). "Methylation of SST was significantly related to several clinicopathologic factors, including tumor size, stage, DAPK methylation, TAC1 methylation, and GALR2 methylation." (PMID 26251921, 2015). "In this study we have found that the proportion of somatostatin producing cells is less than 1% in histologically normal young and adult colonic epithelium, and significantly reduced in tumorous samples." (PMID 25723531, 2015). "An MSP survey of 100 tumor tissue samples demonstrated that hypermethylation of the SST promoter (81%) and SSTR1 promoter (64%) occurred with a high frequency." (PMID 25734919, 2015). "The current findings provide novel direct epigenetic evidence in human patients for the involvement of SST in the process of human tumor suppression." (PMID 25734919, 2015). "Radiolabeled SST analogs can be delivered to transfected tumors, which provides a new specific approach to imaging gene expressions and killing tumor cells." (PMID 25879040, 2015). "SST methylation in 81% of HNSCC tumor specimens significantly correlated with tumor size (P = 0.043), stage (P = 0.008), galanin receptor type 2 (GALR2) methylation (P = 0.041), and tachykinin-1 (TAC1) (P = 0.040)." (PMID 25734919, 2015). "The three somatostatin analogues significantly inhibited GH release in GC tumor cultures, with BIM-23120 showing the highest inhibitory effect (34.3%) followed by octreotide (28.3%) and SOM-230 (19%)." (PMID 26549306, 2015). "Hormone therapy with dopamine agonists (for PRL-producing tumours) and somatostatin analogs (for GH-producing tumours) are used to control the biochemical secretions." (PMID 24520294, 2014). "The anti-neoplastic action of SST analogs depends on the kind of tumor and the receptor subtypes to which they are bound to and occurs through direct and indirect mechanisms." (PMID 24570674, 2014). "Long-acting somatostatin analogs are currently the first-line treatment of choice in this setting, where they provide biochemical control and reduce tumor size in a significant proportion of patients." (PMID 24166706, 2014). "In particular, SST analogs are used frequently to control hormone-related symptoms while their anti-neoplastic activity seems to result prevalently in tumor stabilization." (PMID 24570674, 2014). "The rationale for the employment of SST-analogues to image cancer is both based on the expression of SSTR by tumor and on the high affinity of these compounds for SSTR." (PMID 24693229, 2014). "SSTR2 expression is differentially regulated in various tumor types and therapeutic somatostatin analogs binding to SSTR2 are in clinical use." (PMID 25010045, 2014). "Somatostatin and its receptors sst1, sst2, sst3, and sst5 were expressed with variable frequency in OC tumor cells and in their surrounding stroma, as well as in the stroma of different benign conditions." (PMID 24860785, 2014). "Results showed a strong correlation between SUVmax⁡ and PRRT radionuclide tumor retention in the voxels with the highest uptake suggesting a potential role of 68Ga-labeled SST-analogues PET to estimate the PRRT achievable dose." (PMID 24693229, 2014).
tumor (continued). "As previously reported, the SST analog efficacy depends on the tumor receptor expression patterns, but these are rarely assessed, even if there is evidence of better results on survival obtained with selective treatments." (PMID 24570674, 2014). "SST directly or indirectly influences tumour growth and development through the inhibition of cell proliferation and secretion and induction of apoptosis, even though SST role in hepatocarcinogenesis is still opened to argument." (PMID 25225571, 2014). "SSTR2 is widely and strongly expressed in nervous, endocrine, and tumor tissues, and most of the clinically available somatostatin analogs have a strong SSTR2-binding affinity." (PMID 24587133, 2014). "Other options include the application of novel (radiolabeled) SST analogs with improved tumor uptake and radionuclide retention time, or a combination of PRRT with other systemic therapies, such as chemotherapy or treatment with radio sensitizers." (PMID 24765618, 2014). "It is accepted that somatostatin acts locally on tumor growth, either through direct action on tumor cells and/or through action on peritumoral vessels." (PMID 25111655, 2014). "Among receptors for many regulatory peptides, SST receptors expressed on the membrane of tumor cells have provided the rationale for the development of SST agonists able to selectively target tumor cells." (PMID 23476673, 2013). "Further studies are required to investigate the inhibition of endogenous SST expression in tumor tissues, in addition to exogenous SST expression." (PMID 24260078, 2013). "In this paper the most recent findings on the expression and functional roles of SST and SST receptors in tumor cells are discussed." (PMID 23476673, 2013). "Nowadays, different somatostatin analogs are available not only for therapeutic purposes but also when labeled with b1-emitters (e.g., 68Ga and 64Cu) for tumor imaging with integrated PET/CT scanners." (PMID 23316341, 2012). "In a number of in vitro and in vivo mammary cancer models, SST and its analogs displayed anti-tumor activity for, e.g., OCT decreases the growth of ER+ cell lines in culture." (PMID 24281555, 2012). "Analogues of somatostatin are used to control symptoms of hormonal overproduction by NETs, but they also exhibit an antiproliferative effect on tumor cells in vitro." (PMID 23227348, 2012). "Somatotropin release-inhibiting factor (somatostatin) acts by signaling through specific receptor subtypes to suppress growth hormone (GH) secretion by pituitary somatotroph tumor cells." (PMID 22574156, 2012). "Lastly, SST analogs have been used as a first option therapy in selected patients upon its ability to reduce hormonal release and/or to inhibit tumor mass progression." (PMID 23162532, 2012). "No tumors predominantly expressed insulin, pancreatic polypeptide, or somatostatin, although some harbored focal aggregates of tumor cells expressing one of those hormones." (PMID 21853126, 2011). "The antineoplastic action of SST analogues depends on the kind of tumour and the receptor subtypes they are bound to, and occurs through direct and indirect mechanisms." (PMID 20196864, 2010). "As previously said, the SST analogue efficacy depends on the tumour receptor expression patterns, but these are rarely assessed, even if there is evidence of better results on survival obtained with selective treatments." (PMID 20196864, 2010). "Biological response to somatostatin analogs depends on distribution and level of expression of SSTRs subtypes in tumours, and the expression of selective somatostatin receptor-signaling pathway molecules." (PMID 20196864, 2010). "In these nine cases with βHCG positive tumor cells, six cases were accompanied by gastrin, somatostatin and/or serotonin positive tumor cells." (PMID 20594358, 2010). "Tumor cells of both epithelioid and ganglion-like cell types showed positive reactivity for synaptophysin, somatostatin, and CD56." (PMID 20444291, 2010).
tumor (continued). "In order to have an exclusive and direct access to thepancreatic somatostatin cells and to avoid mixtures of cell types from isletcell cultures, investigators established and cloned a transplantable rat isletcell tumor which secretes insulin and somatostatin." (PMID 20011057, 2009). "The endocrine cells in appendiceal tumour nests were chromogranin A-, somatostatin-, synaptophysin- (Figure." (PMID 18252007, 2008). "In our laboratories, camptothecin (CPT), a potent anti-tumor agent, has been successfully coupled to urotensin, BM, and SST analogs." (PMID 21892324, 2008). "We found that BON and IMR32 cells have higher binding affinity, with other 3 tumor cells showing weak binding to SST-14." (PMID 21892324, 2008). "In our previous studies, cytotoxic conjugates of SST and BN analogs have revealed some utility against tumor growth and angiogenesis." (PMID 21892324, 2008). "Additionally, we evaluated the effect of the bifunctional chelator (BFC) on the pharmacokinetic properties and tumor uptake by labeling the SST agonist Tyr3-octreotate (TATE) with copper-61 using two different conjugates: DOTA-TATE and NOTA-TATE." (PMID 39909885, 2025). "Distinctive morphological features, such as frequent tubular architecture, and a characteristic immunoprofile (common MUC1 positivity and rare SSTR2 A expression, in addition to somatostatin expression and tumor location), help to identify ampullary Som-NETs among NF-Duo-NETs." (PMID 40347392, 2025). "Downregulation of SST is partly attributed to higher methylation levels of SST in tumor tissues." (PMID 39949372, 2025). "The presence of glandular structures in FNB specimens, especially when obtained from pancreatic head masses, opens at least two differential diagnoses: (i) primary ampullary somatostatin-producing tumor infiltrating the pancreatic head; and (ii) well-differentiated ductal adenocarcinoma." (PMID 40668487, 2025). "In the setting of NET, the cellular target is represented by the SST overexpressed on tumor cells." (PMID 38581469, 2024). "Kaplan–Meier analysis showed that neither immunoexpression of SST nor any of the SSTRs in tumor samples was significantly associated with the survival probability of CRC patients." (PMID 39518025, 2024). "Furthermore, the tumor uptake of the radiolabeled somatostatin analogs continued to increase up to approximately 12 h p.i." (PMID 39464654, 2024). "Tetradecapeptide SST inhibits tumour growth by blocking growth factor pathways." (PMID 39011594, 2024). "Unlike other authors, we observed a more heterogeneous SST immunoexpression, ranging from single SST-positive cell EECs to a strong IHC reaction present in numerous cells of altered adenocarcinoma structures, or within the stroma of the tumor." (PMID 39518025, 2024). "Additionally, SST expression was demonstrated in the structures of the nervous system present in the tumor, where it also co-expressed with other NPs, e.g., protein gene product 9.5 (PGP 9.5), substance P (SP) and calcitonin gene-related peptide (CGRP)." (PMID 38540191, 2024). "Both NCs and vascular endothelium within the tumor expressed SST." (PMID 38540191, 2024). "Additionally, fluorescent somatostatin analogs were used in order to delineate tumor boundaries for SSTR2-expressing tumors during surgery." (PMID 39329930, 2024). "Interestingly, conjugate prepared with SST analogs OCT has shown better outcome in tumour growth blockade even in case of tumour which exhibits a low expression of SSTR subtype." (PMID 38203605, 2023).
tumor (continued). "The SST-mediated in vivo and/or in vitro antiproliferative effect in the tumour is considered direct via activation of five different somatostatin receptor subtypes (SSTR1-5), which are well expressed in most tumours and often more than one receptor in a single cell." (PMID 38203605, 2023). "Furthermore, in comparative studies, SST analogues, namely AN-162 with cytotoxic effect, exhibit a higher degree of tumour growth inhibition in comparison to doxorubicin alone in triple-negative breast cancer expressing SSTR subtypes." (PMID 38203605, 2023). "Taken together, all the information available regarding the use of SST analogs with variable efficacy in the treatment of pituitary adenomas shows that they play a significant role in tumour shrinkage and suppression of tumour size in a large number of patients." (PMID 38203605, 2023). "SST, a growth hormone inhibitory peptide, emerged as an efficient peptide with an antiproliferative effect in most peripheral tissues and in vitro cultured cells, specifically in tumours of different origins." (PMID 38203605, 2023). "The presence of SSTR subtypes in the vasculature of different neoplasms and specifically the presence of SST in peritumoural veins might serve as an effective defense mechanism in angiogenesis and events associated with angiogenesis." (PMID 38203605, 2023). "In addition, SST and its analogues mediate its effect via increased apoptosis of cancer cells, decreased tumour cell growth and angiogenesis." (PMID 38203605, 2023). "Additionally, somatostatin and analogues’ role in hormone secretion regulation, tumor growth, and survival is emphasized, presenting relevant therapeutic examples." (PMID 38201544, 2023). "However, research findings regarding the role of SSTR and SST signaling in NETs depend on tumor type as well as on other tumor-specific factors." (PMID 38201544, 2023). "In line with these and our observations, somatostatin analogs modified with weaker albumin binders such as the 4-(p-chlorophenyl)butanoate or 4-(p-bromophenyl)butanoate entities showed faster tumor accumulation when compared with the analog modified with the 4-(p-iodophenyl)butanoate entity." (PMID 37686538, 2023). "In addition to the direct action of SST in the regulation of tumour growth, the indirect action of SST analogs is involved in the regulation of growth hormone secretion and angiogenesis with a plausible mechanism involving the inhibition of VEGF." (PMID 38203605, 2023). "Additionally, while somatostatin analogs can control symptoms and delay disease progression, their ability to effectively reduce tumor size is limited." (PMID 38201544, 2023). "The superiority of 177Lu-satoreotide tetraxetan over [177Lu]Lu-DOTA-TATE and other SST agonists such as [177Lu]Lu-DOTA-TOC in inhibiting tumour growth was also noted in other in vivo therapy studies, which applied different animal models and treatment regimens." (PMID 36145306, 2022). "Importantly, somatostatin also acts on tumor cells inhibiting hormone hypersecretion and cell proliferation, as reported in different tumor types including somatotropinomas, PanNETs, and thyrotropinomas, which abundantly express SSTs." (PMID 34601790, 2022). "Therefore, expression of the corresponding somatostatin receptors in target cells is the basis for the biological activity of SST-14, and screening the expression of sstrs in tumor cells is the first thing to do." (PMID 36207478, 2022). "In vitro response of tumor tissue to somatostatin may better predict tumoral in vivo responses of somatostatin analogs than somatostatin receptor immunohistochemistry." (PMID 35602875, 2022). "Only a few patients with NETs are amenable to curative tumor resection, and for most patients, only palliative treatments to successfully control the disease or manage symptoms remain, such as with synthetic somatostatin (SST) analogs (SSAs), such as octreotide (OCT) or lanreotide (LAN)." (PMID 36555512, 2022).
tumor (continued). "Therefore, oncolytic virus delivery system was introduced to express somatostatin fusion protein and the anti-tumor effects of both somatostatin and oncolytic virus were combined to destroy tumor tissues." (PMID 36207478, 2022). "This has led to the development of chimeric somatostatin–dopamine agonists that could more effectively inhibit tumour progression." (PMID 35163374, 2022). "However, preclinical studies in mice have found a significantly higher tumor uptake with somatostatin antagonist as well as a longer survival and better tumor control." (PMID 35158852, 2022). "The levels of the neuropeptides Calcitonin Gene-Related Peptide (CGRP), Substance P (SP), and somatostatin were measured from tumor tissue homogenates using radioimmunoassay, while tumor structure and peritumoral inflammation were evaluated by conventional use of CD31, CD45 and CD3 immunohistology." (PMID 34336669, 2021). "Since most of the knowledge on the epigenetic regulation of the SST-system is derived from in vitro studies in cell lines and experimental tumor models, future studies should also focus on the role of epigenetic marks in determining SSTR expression in primary NET tissues from patients." (PMID 33085037, 2021). "However, SST expression appears to decrease with tumor grading and is lower in poorly differentiated CRC or mucinous subtype of CRC with signet-ring cells." (PMID 34829972, 2021). "Moreover, epigenetic reprogramming of PANC-1 cells with 5′-Aza did not only increase NGN3, INS, and SST expression but also induced a less aggressive phenotype with impaired tumor growth and improved response to the cytotoxic drug gemcitabine." (PMID 34771704, 2021). "In addition, preclinical studies showed that the SST-SSTR interaction has tumor suppressor activity in certain tumors." (PMID 33085037, 2021). "All mechanisms leading to reduced or absent SST expression in CRC in vivo may result in impaired anti-tumor effects of this neuropeptide." (PMID 34829972, 2021). "Like AE, somatostatin (SST) and derivatives thereof affect a broad range of biological pathways resulting in metabolic, cathartic, cell proliferation, cell survival effects and, notably, antineuroectodermic tumor activity." (PMID 33990938, 2021). "Consequently, synthetic SST analogues (SSAs) represent an attractive therapeutic target to treat the SST-positive tumor pathologies controlling hormone hypersecretion and tumor growth." (PMID 34638313, 2021). "SST inhibitory actions are mediated through their so-called SST receptors (SSTs), which are widely distributed in normal and tumor tissues, and regulate, among other activities, cell proliferation, differentiation, and angiogenesis in many tumor types." (PMID 34638313, 2021). "Studies have shown that chimeric DA-SST compounds are more efficacious than individual DA and/or SST analogues, either alone or combined, in inhibiting secretion from primary cultures of human somatotroph and lactotroph tumor cells." (PMID 32591776, 2020). "Several studies performed on somatostatin and its analogs have also shown that tumor cells synthesize cytokines that favor escape from immunosurveillance and may also act as tumor growth factors." (PMID 32766136, 2020). "Moreover, somatostatin is capable of indirectly suppressing tumor growth by the inhibition of angiogenesis and modulation of the immune system." (PMID 32545257, 2020). "Obviously, SST hypermethylation is a general and common process in a broad range of tumors, suggesting that somatostatin may function as a tumor suppressor." (PMID 32243066, 2020). "Also, real‐time qPCR was performed for quantifying SST gene expression in normal and tumor tissue samples." (PMID 32243066, 2020). "The inhibitory effects of SST on tumor cells have received increasing attention in recent years." (PMID 32462020, 2020).